IL1B (interleukin 1 beta)
Diseases named in the same sentence as IL1B in open-access papers (continued):
Sharing a sentence is not in itself a finding about the gene and the disease.
AIDS (continued). "Therefore, as demonstrated in multiple studies targeted IL-1β blockade has been an effective approach in a broad spectrum of AIDs." (PMID 36203564, 2022). "Dapansutrile inhibits subsequent activation of IL-1β and is currently tested in the treatment of gout, autoimmune encephalitis and may also carry a large potential in the treatment of AIDs." (PMID 33603750, 2020). "In AIDS patients, serum IL-1β levels correlate with the progression and severity of the disease." (PMID 31774879, 2019). "Most AIDs are caused by a lacking regulation in the inflammasome, a large intracellular multiprotein platform, leading to an overproduction of IL-1β that plays a predominant pathogenic role in such disorders." (PMID 30999610, 2019). "IL-1β blockade results in a sustained reduction of disease severity in most AIDs." (PMID 30999610, 2019). "The auto-inflammatory diseases (AIDs) cover a wide spectrum of systemic inflammatory diseases ranging from rare Mendelian to polygenic disorders whose pathogenesis lies in deregulation of interleukin-1 beta (IL-1β) secretion." (PMID 25758134, 2015). "Thus, chronic diarrhea and/or weight loss in African AIDS patients is associated with increased levels of macrophage related cytokines (TNF-α and IL-1β) and chemokines (CCL2) compared to HIV-negative healthy controls." (PMID 26475133, 2015). "Collectively, these findings indicate that macrophages in the colon of African AIDS patients with diarrhea and/or weight loss have an activated CD14+ phenotype and express pro-inflammatory cytokines (TNF-α, IL-1β) that are known to be induced by LPS–mediated activation of CD14+ macrophages." (PMID 26475133, 2015). "TNF-α+ and IL-1β+ CD68-positive macrophages were present in the lamina propria of AIDS patients." (PMID 26475133, 2015). "Therefore, the sustained high expression of IL-1β may be one of the reasons for poor immune reconstruction in AIDS patients." (PMID 35003070, 2021). "We recently report strong PD-1/PD-L1/PD-L2 expression in AIDS-KS tissues, and that KSHV lytic reactivation further induces PD-L1 expression from tumor cells through IL1β." (PMID 36457850, 2022). "In the clinic, some cytokines induced by TLRs are immunotherapeutic targets in AIDs, such as TNF-α, interleukin (IL)-6, interferon (IFN)-α, and IL-1β." (PMID 35126357, 2021). "A growing experience with the human IL-1 receptor antagonist, Anakinra (ANA), and the monoclonal anti IL-1β antibody, Canakinumab (CANA), has also been engendered, highlighting their efficacy upon protean clinical manifestations of AIDs." (PMID 30999610, 2019). "A decrease of miR-146a level results in increases of type I IFN and pro-inflammatory cytokines, such as IL-1β and TNF-α, which are involved in the pathogenesis of various AIDs." (PMID 29190882, 2017). "There is a report demonstrating that the levels of TNF-α, IL-1β and IL-8 are significantly higher in asymptomatic HIV-infected African women than women living with AIDS, suggesting the role of cytokines in early phase of HIV infection." (PMID 25879453, 2015). "IHC staining indicated that there was a marked increase in proinflammatory cells expressing IL-1β (median 174 vs. 75 cells/0.8 mm2, p = 0.04) and TNF-α (median 226 vs. 107 cells/0.8 mm2, p = 0.01) in the colon of AIDS patients compared to healthy controls." (PMID 26475133, 2015). "IL-1β and IL-18, potent pro-inflammatory cytokines and primary outputs of the activated NLRP3 inflammasome, play crucial roles in the development of various inflammatory and AIDs." (PMID 38666950, 2024). "The discovery of the increased production of IL-1β as the main pathogenetic mechanism in many inflammasomopathies led to the introduction of anti-IL1 agents and other biologic agents in the management of AIDs." (PMID 34198614, 2021). "The unifying pathogenetic mechanism of AIDs relies in a lacking regulation of the inflammasome which leads to overproduction of proinflammatory cytokines, especially IL-1β." (PMID 25784780, 2015).
AIDS (continued). "To determine whether macrophages were contributing to the pro-inflammatory milieu in the colon of AIDS patients, we performed double labeling of CD68+ macrophages with TNF-α and IL-1β using a dye swap method with validation by fluorescence microscopy." (PMID 26475133, 2015). "Interestingly, whereas inflammatory cytokines IL-8 and IL-1β prevent in vitro PMN death, the levels of those cytokines were low in RMs progressing towards AIDS." (PMID 19317901, 2009).
cholestasis (38 papers, 2004 to 2025). Impairment of the bile flow caused by obstruction within the liver, or outside the liver in the bile duct system. "Levels of IL-6, TNF-α, IL-10, and IL-1β in liver tissue reflect the degree of hepatic inflammation caused by cholestasis, while serum levels of TC, TG, LDL-C, and HDL-C reflect lipid metabolism and oil red O staining visualizes lipid accumulation in liver tissue." (PMID 38523644, 2024). "Furthermore, reduced farnesoid x receptor (FXR) signaling is thought to induce activation of the macrophage inflammasome in cholestasis and endotoxemia, thereby promoting IL-1β release and increasing immune susceptibility in cholestasis." (PMID 33411796, 2021). "According to a prior study, dexamethasone therapy restored the inflammation caused by cholestasis, as evidenced by histological findings and a significant decrease in many inflammatory markers (TNF-α, IL-1β, and IL-6)." (PMID 41517447, 2025). "Further studies have shown that the development of cholestasis in response to LPS treatment is largely due to increased production of inflammatory cytokines, particularly IL-1β and tumour necrosis factor-α (TNF-α)." (PMID 39680527, 2024). "The positive relationship between the levels of hulncRNA57RIK in the monocytes/macrophages and the levels of IL-1β in the sera of patients with cholestasis was also observed." (PMID 39664579, 2024). "In this regard, dysregulation of the localization, protein levels and transcript expression of proteins in bile salt transport are essential mechanisms by which LPS and inflammatory cytokines such as TNF-α and IL-1β lead to the development of cholestasis." (PMID 39680527, 2024). "Altered expression of CR-dependent regulatory genes during PNAC accompanies cholestasis and is, in part, due to increased cytokine (IL-1β and TNFα) production." (PMID 37647292, 2023). "Cholestasis can trigger the release of cytokines such as IL-6, IL-1β, and TNF-α, which, in turn, repress NTCP transcription." (PMID 35495620, 2022). "It was demonstrated that ANIT-induced cholestasis increased the levels of IL-1β, IL-6, and TNF-α and decreased the levels of IL-10." (PMID 36409145, 2022). "The protective effects of fenofibrate and DCHT on ANIT-induced cholestasis and liver injury coincident with the inhibition of mRNA expression of inflammation-related genes (Il6, Il1b, and Tnfa), as well as the suppression of JNK/SAPK, NF-ĸB and STAT3 pathways." (PMID 35370715, 2022). "The expression levels of serum inflammatory cytokines, such as tumor necrosis factor-α (TNF-α), interleukin (IL)-1β, and IL-6, are increased in patients with cholestasis, demonstrating that inflammation plays a role in cholestasis." (PMID 35924060, 2022). "Our data showed that IL-1β and IL-6 were prominently reduced in liver with EE-induced cholestasis by KD treatment." (PMID 34064649, 2021). "To elucidate the pharmacological effects of KD on the alleviation of EE-induced cholestasis, we tested the protein expression of IL-1β and IL-6, known as pro-inflammatory cytokines, by Western blotting." (PMID 34064649, 2021). "Cholestasis is also an inflammatory disease characterized by elevated IL-1β and IL-6 levels in liver." (PMID 34064649, 2021). "Mechanistically, IL-1β appears to mediate cholestasis in PNAC through hepatocellular NF-κB signaling, which interferes with the ability of FXR to bind to and transactivate Abcb11 and Abcc2 promoters, thus reducing canalicular bile and bilirubin transport." (PMID 29643332, 2018). "The observation that increased transcription of Il1b at 3 days preceded elevated serum bilirubin, bile acids, AST and ALT suggested a causative role for IL-1β in the development of cholestasis." (PMID 29643332, 2018). "Genetic and pharmacological blockade of IL-1β signaling both normalized bile transporter expression and attenuated cholestasis and hepatocyte injury in the PNAC model." (PMID 29643332, 2018).
cholestasis (continued). "Taking these findings into account, it seems likely that the CXCR2-mediated feedback mechanism described here may be relevant at least for the part of inflammation-induced cholestasis mediated by IL-1β." (PMID 39680527, 2024). "Accordingly, blocking the action of IL-1β or TNF-α with an antibody directed against the IL-1β receptor or a TNF-α inactivating fusion protein results in a reduction of LPS-induced cholestasis, which was almost completely abolished by combined inactivation of IL-1β and TNF-α." (PMID 39680527, 2024). "Moreover, Q7R can also reduce TNF-α, IL-1β, PTGS1, PTGS2, NCOA2, and NF-κB levels and alleviate the inflammatory response caused by cholestasis." (PMID 36699093, 2022). "Similarly, CAR activation by TCPOBOP reduced cholestasis-induced liver dysfunction, inflammation (p65 nuclear translocation, mRNA expression of TNFα, IL-1β, IL-6) and oxidative stress." (PMID 34502180, 2021). "Similarly, macrophages have been associated with the pathogenesis of murine parenteral nutrition-associated cholestasis via toll-like receptor 4 (TLR4)-mediated activation and production of interleukin-1 beta (IL-1β)." (PMID 33411796, 2021). "In support of this hypothesis, treatment with dexamethasone counteracted cholestasis-related hepatic inflammation by preventing NFκB translocation to the nucleus and restored TNFα, IL-6, and IL-1β mRNA levels in the liver of cholestatic rats." (PMID 33198224, 2020). "Dramatical increase of IL-1β during cholestasis indicates the presence of inflammasome activation." (PMID 27924062, 2016). "For example, TNF-α and IL-1β play important roles in cholestasis-induced cell death and fibrosis." (PMID 27872855, 2016). "However, the fact that cholestasis induced by an LPS-induced inflammatory response can only be attenuated by the combined administration of antagonistic antibodies against both TNF-α as well as IL-1β suggests that IL-1β has a relevant role in this context." (PMID 39680527, 2024). "IL-1β increases hepatocyte NF-κB signaling, which interferes with farnesoid X receptor and liver X receptor bonding to respective promoters of canalicular bile and sterol transporter genes (Abcc2, Abcb11, and Abcg5/8), resulting in transcriptional suppression and subsequent cholestasis." (PMID 29643332, 2018). "IL-1β, IL-6, TNF-α, and IL-10 are common indices used to assess the inflammatory response, oxidative stress, and apoptosis, among others, in cholestasis." (PMID 36409145, 2022). "Previous studies by our group demonstrated that inhibition of the JNK signaling pathway completely blocked IL-1β-mediated suppression of RXRα-dependent Ntcp gene expression, thus implicating JNK to be a central player in inflammation-induced cholestasis." (PMID 15312234, 2004). "The mice underwent BDL to induce cholestasis, increase the expression levels of the inflammatory markers TNF-α and interleukin-1beta (IL-1β), decrease the expression of the anti-inflammatory cytokine IL-10, and trigger inflammation and HF by upregulating TGF-β1/Smad2/α-SMA." (PMID 39859410, 2025). "The disruption of the blood supply to liver cells as a consequence of cholestasis significantly contributes to the inhibition of the activity of protein biliary transporters, which may be reflected in elevated levels of TNF-α, IL-1β (interleukin-1β), and IL-6." (PMID 37834802, 2023). "Inflammatory factors, including tumor necrosis factor-α (TNF-α), interleukin-1 β (IL-1β), interleukin- 6 (IL-6), transforming growth factor-β (TGF-β), are involved in drug-induced liver injury, cholestasis, alcoholic and non-alcoholic fatty liver diseases, and other chronic liver disease processes." (PMID 34366845, 2021). "Besides, the pro-inflammatory cytokines differently regulate hepatic transporters depending on the mechanism of cholestasis; indeed, TNF-α and IL-1β downregulate the bile salt export pump (BSEP) and decrease BAs secretion." (PMID 31546715, 2019).
cholestasis (continued). "On the other hand, PE resveratrol and ginsenosides have been surprisingly reported as anti-cholestatic agents in the EE murine model, evidenced by reduced levels of biochemical markers of cholestasis, oxidative stress, as well as of the pro-inflammatory cytokines TNF-α, IL-6, and IL-1β." (PMID 31546715, 2019). "Histological findings and a significant drop in several markers of inflammation (p65 nuclear translocation, mRNA expressions of TNF-α, IL-1β, IL-6) showed that DEX treatment reversed cholestasis-induced inflammation, and similar results have been obtained with oxidative stress markers." (PMID 30252871, 2018). "However, in advanced cholestasis, RIO treatment resulted in a significant decrease of TNFα mRNA and tended to reduce MCP1 expression, while VCAM and IL1β remained unchanged." (PMID 29921982, 2018).
edema (38 papers, 2013 to 2026). An abnormal accumulation of fluid beneath the skin, or in one or more cavities of the body. "Anti-inflammatory activity was evaluated in vitro using tumor necrosis factor-alpha (TNF-α)-induced interleukin-1 beta (IL-1β) production in human keratinocyte (HaCaT) cells, and in vivo using a carrageenan-induced rat paw edema model." (PMID 41304926, 2025). "This study demonstrated that the balance of prostaglandins and leukotrienes is a pivotal mechanism that control interleukin-1β (IL-1β) production, a main mediator involved in the pathophysiology of pulmonary edema (a manifestation of severe envenoming cases)." (PMID 39628768, 2024). "Brain edema is accompanied by IL-1β, IL-6, and TNF-α cytokines, exacerbating mitochondrial dysfunction and increasing ROS levels, leading to neuronal inflammation." (PMID 37529169, 2023). "The enhanced effects of inflammation were reduced by molecular hydrogen treatment at attenuating acute cerebral oedema and significantly reduced the level of the inflammatory cytokine IL-1β." (PMID 35895245, 2023). "Reduced levels of COX-2, NO, TNF-α, and IL1-β in tissues obtained from λ-carrageenan-induced paw oedema mice." (PMID 35744969, 2022). "Besides, as a powerful pro-inflammatory cytokine, the IL-1β can activate additional inflammatory cells, accelerating the release of inflammatory mediators, causing a rise of inflammation cascade, amplifying the damage signals, and finally leading to pulmonary edema." (PMID 36364151, 2022). "According to previous reports the extract of CM containing 15 and 30 mg of total phenols/b.w./day reduced IL-1β after 2 h, 24 h, and 48 h from induction of inflammation with carrageenan in paw oedema model in rats." (PMID 34834710, 2021). "After treatment with the miR-124-3p agomir, the degrees of pulmonary injury (e.g. alveolar hemorrhage and interstitial edema), and the increases in IL-1β, IL-6, and TNF-α levels induced by LPS were significantly attenuated." (PMID 32391561, 2020). "Previous studies have shown that cytokines, such as TNF-α and IL-1β released from microglia under hypoxic-ischemic and inflammation conditions, are closely related to cerebral edema because they can disrupt the endothelial’s tight junction." (PMID 24916922, 2014). "We found that AA treatment significantly alleviated radiation-induced lung histopathological damage, reduced inflammatory cytokines IL-1β, IL-4, IL-6, IFN-γ in BALF, mitigated oxidative stress, and improved pulmonary edema and overall health status." (PMID 41564102, 2026). "Meanwhile, 3,5-di-O-caffeoylquinic acid was reported to show an anti-inflammatory effect in the carrageenan-induced rat paw edema model through the suppression of TNF-α and IL-1β dose-dependently." (PMID 37667314, 2023). "In these lung protective studies, shionone suppressed the inflammatory response, marker genes, and pathways, such as pulmonary edema, TNF-α, IL-6, and IL-1β and ECM1/STAT5/NF-κB, which again support the anti-inflammatory properties of shionone." (PMID 38202771, 2023). "Our results suggest a reduced expression of pro-inflammatory cytokines including TNF-α, IL-6, IL-1β, and MMP-13 in the ASPP 092 treated ear of the mice in a dose-dependent manner when compared to that of the EPP-induced ear edema mice those are untreated." (PMID 34588910, 2021). "A study showed that administration of poly-ε-caprolactone microsphere polymers containing usnic acid reduced significantly IL-1β, TNF-α, and NO levels in carrageenan-induced paw edema in a rat model, results of which were similar to our findings." (PMID 32963745, 2020). "Studies on the mechanisms suggest that in the early stage of SILI, smoke particles stimulate the body's inflammatory cells to release a large number of inflammatory cytokines such as IL‐1β, IL‐6, TNF‐α, resulting in increased vascular permeability and pulmonary edema." (PMID 39588955, 2024).
edema (continued). "We observed neutrophil recruitment and pulmonary edema at the earliest on Day 1 following bleomycin treatment suggesting it may result from the early increase of TNF‐α and IL‐1β." (PMID 36898724, 2023). "Further an investigation also disclosed that the ethyl acetate extract of S. montagneana decreased LPS-induced iNOS protein expression in RAW 264.7 cells and suppressed pro-inflammatory mediators, such as iNOS, IL-1β, and myeloperoxidase (MPO), in carrageenan-induced rat paw edema." (PMID 38136188, 2023). "In the intracranial hemorrhage (ICH) model, CBL can ameliorate secondary injury and promote behavioral performance during the acute phase by reducing brain edema, the inflammatory response, and BBB permeability by decreasing the expression levels of IL-1β, TNF-a, IL-6, and AQP4." (PMID 36074398, 2022). "Similarly, elevated CSF levels of IL-1β, a potent inducer of ILC3 activation, correlated with the development of cerebral edema and poor neurological outcomes after human TBI." (PMID 33427206, 2021). "In the study, it was found that after DCXC treatment with 10, 30 and 60 mg/kg, inflammatory cell exudation and pulmonary edema were alleviated to a certain extent, and the levels of TNF-α, IL-6 and IL-1β in BALF were also reduced to a certain extent in a dose-dependent manner." (PMID 31186277, 2019). "Since curcumin reduced also acute IL-1β expression in pericontusional astrocytes and attenuated IL-1β-induced AQP4 expression in cultured astrocytes, the authors suggested that IL-1β may promote cerebral edema via the regulation of AQP4." (PMID 26346093, 2015). "This study showed that high tidal volume ventilation increased total protein, IL-1β, IL-6, RANTES, neutrophil counts, and MPO activity in the BALF and induced lung edema, GEF-H1 and active RhoA expression, Rho-kinase activation, and ultrastructural evidence of endothelial destruction." (PMID 25019086, 2014). "This suggests that inhibition or suppression of microglial activation and release of TNF-α and IL-1β might ameliorate BBB disruption and cerebral edema." (PMID 24916922, 2014). "In vivo, pulmonary inflammation, pulmonary edema, ultrastructure changes of type II alveolar epithelial cells, MPO activity, total cells, neutrophils, macrophages, TNF-α, IL-6 and IL-1β in BALF, along with the expression of VCAM-1 and VEGF were dose-dependently attenuated by andrographolide." (PMID 23437127, 2013).